CLN6 (CLN6 transmembrane ER protein)
Synonyms: FLJ20561; HsT18960; nclf; CLN4A; CLN6A
Tractability: Antibody: UniProt predicts a signal peptide or a membrane-spanning region. PROTAC: its protein half-life has been measured.
Gene: Protein-coding gene on chromosome 15 (68,206,992 to 68,257,211, reverse strand). Ensembl gene ENSG00000128973.
Subcellular location: Endoplasmic reticulum membrane; Endoplasmic reticulum
Subcellular location (Human Protein Atlas): Endoplasmic reticulum; Nucleoli; Vesicles
Gene Ontology:
Molecular function: lysophosphatidic acid binding; protein binding; protein homodimerization activity; sulfatide binding
Biological process: cholesterol metabolic process; ganglioside metabolic process; glycosaminoglycan metabolic process; lysosomal lumen acidification; positive regulation of proteolysis; lysosome organization; protein catabolic process
Cellular component: early endosome; endoplasmic reticulum; endoplasmic reticulum lumen; membrane; membrane raft; endoplasmic reticulum membrane
Genetic constraint (gnomAD): Loss-of-function variants: 21 observed, 29.8 expected, observed/expected ratio (o/e) 0.7, 90% interval 0.5 to 1.01. The upper end of that interval is the gene's LOEUF score, 1.01, which puts it in group 4 of 6, group 1 being the genes least tolerant of losing a copy. Missense variants: 377 observed, 407.91 expected, observed/expected ratio (o/e) 0.92, 90% interval 0.85 to 1.01. Synonymous variants: 197 observed, 171.48 expected, observed/expected ratio (o/e) 1.15, 90% interval 1.02 to 1.29.
Gene-disease validity (ClinGen):
ClinGen rates the evidence that CLN6 causes each of these diseases.
neuronal ceroid lipofuscinosis (autosomal recessive): Definitive.
Homologues: Orthologues: macaque CLN6 (97% identical), dog CLN6 (91% identical), pig CLN6 (91% identical), mouse Cln6 (90% identical), rabbit CLN6 (89% identical), rat Cln6 (89% identical), guinea pig CLN6 (89% identical), tropical clawed frog cln6 (70% identical), zebrafish cln6b (57% identical), chimpanzee CLN6 (46% identical).
Diseases named in the same sentence as CLN6 in open-access papers:
CLN6 is named in the same sentence as 50 diseases in open-access papers, as found by Europe PMC text mining. Sharing a sentence is not in itself a finding about the gene and the disease. The quoted sentences say what the papers report.
Batten disease (15 papers, 2011 to 2025). "In support of this, central retina versus medial or peripheral retina, was preferentially treated when mice with CLN6 deficiency which causes late infantile Batten disease, received intra‐CSF AAV9‐based gene replacement." (PMID 39123298, 2024). "While there are many subforms of Batten disease, the CLN6 variant arises from various mutations in the CLN6 gene, the most common of which leads to a frameshift mutation and ultimate loss of expression of the CLN6 protein." (PMID 32269836, 2019). "CLN6-Batten disease, resulting from mutations in CLN6, constitutes two distinct diseases: a pediatric form, also referred to as variant late infantile neuronal ceroid lipofuscinoses, and a rare, less-severe adult-onset form referred to as Kufs type A disease." (PMID 30665444, 2019). "There have only been a few case reports on late-infantile Batten disease caused by mutations in CLN6 that include MRI, and in these the pathology varied markedly between patients, even in consanguineous patients carrying the same gene mutation." (PMID 26161747, 2015). "Sheep that are homozygous for a natural mutation in CLN6 have an ovine form of Batten disease Here, we used in vivo magnetic resonance imaging to track brain changes in 4 unaffected carriers and 6 affected Batten disease sheep." (PMID 26161747, 2015). "Animal models that closely match the disease causing mutation in humans, like the Cln6 ovine model of Batten disease (BD), can be particularly useful in determining the pathophysiology of disease, and for devising new therapeutic strategies for diseases." (PMID 26329332, 2015). "Mutations in CLN6 cause late-infantile juvenile NCL (JNCL) adult-onset NCL, and Kufs disease." (PMID 34868216, 2021). "CLN6 variants were described for the first time in 1997 to be associated with Batten disease." (PMID 34868216, 2021). "While CRMP2 has been studied rather extensively in its role in neuronal trafficking, polarization, and differentiation, and has been associated with CLN6 and Batten disease features, there has been limited study in its use as a therapeutic target in neurodegenerative diseases." (PMID 32269836, 2019). "We conducted in vivo MRI scans of the brains of 4 unaffected heterozygous carriers of CLN6 mutation (here after described as control sheep) and 6 homozygous Batten disease affected sheep (hereafter described as Batten disease affected sheep) over a period of 5 months." (PMID 26161747, 2015). "Despite different cellular localisations of mature lysosomal CLN5 and the ER-resident CLN6, there are similar manifestations of brain pathologies between CLN5 and CLN6 Batten disease." (PMID 33792748, 2021). "Here, we broadly explored the therapeutic potential of CRMP2 modulation in a mouse model of CLN6-Batten disease." (PMID 32269836, 2019). "Here we test the efficacy of S-N-benzy-2-acetamido-3-methoxypropionamide ((S)-Lacosamide), a CRMP2 modulating functionalized amino acid, in CLN6-Batten disease." (PMID 32269836, 2019). "In particular, our study is merely descriptive of the therapeutic utility of (S)-Lacosamide in CLN6-Batten disease." (PMID 32269836, 2019). "We suggest that MRI will be particularly useful for providing a ‘readout’ for determining the efficacy of treatments in sheep models, not only for CLN6 Batten disease, but also for other neurodegenerative diseases where sheep models exist." (PMID 26161747, 2015). "We exemplify several existing naturally occurring ovine variants in genes that are orthologous to human disease genes, such as the Cln6 sheep model for Batten disease." (PMID 26329332, 2015). "Mutations in the CLN6 gene cause a variant late infantile form of neuronal ceroid lipofuscinosis (NCL; Batten disease)." (PMID 23516525, 2013). "CLN6-Batten disease is a rare, autosomal recessive, neurodegenerative disorder with no cure." (PMID 32269836, 2019).
Batten disease (continued). "As (S)-Lacosamide has recently been shown to specifically inhibit CRMP2 phosphorylation via cyclin-dependent kinase 5 (Cdk5), we hypothesized that treatment with (S)-Lacosamide would prove to be therapeutic in models of CLN6-Batten disease." (PMID 32269836, 2019). "In this study, we investigate whether sex differences in a mouse model of CLN6-Batten disease impact disease onset and progression." (PMID 30665444, 2019). "In conclusion, we sought to test whether modulation of CRMP2 activity would prove to be therapeutic in a mouse model of CLN6-Batten disease." (PMID 32269836, 2019). "Notably, studies in the Cln6 model of Batten disease revealed that male mutant mice accumulate more storage material in the somatosensory cortex and thalamus at 2 months of age, whereas female Cln6 mutant mice surpass males in storage material by 6 months of age in these same regions." (PMID 41199165, 2025). "Recent investigations of other subforms of Batten disease (CLN1, CLN3, CLN6) have emphasized the influence of biological sex on disease and treatment outcomes; however, little is known about sex differences in the CLN8 subtype." (PMID 36369162, 2022). "In addition, efficacy with AAV9 has also been demonstrated in multiple Batten diseases, including CLN3, CLN6, and CLN8, using other routes of administration." (PMID 35025759, 2022). "CLN6-Batten disease is a rare neurodegenerative disorder with no cure, characterized by accumulation of lipofuscin in the lysosome, glial activation, and neuronal death." (PMID 32269836, 2019). "Subcortical pathology has not been well mapped in CLN6 Batten disease sheep, and basal ganglia pathology has not been shown in late-infantile disease caused by CLN6 mutations, although it is pronounced in some other late-infantile forms." (PMID 26161747, 2015). "We do not know if sleep abnormalities are present in CLN6 Batten disease sheep, although from the regions that are atrophied we predict that they would be present." (PMID 26161747, 2015). "Therefore, modulation of CRMP2 activity via (S)-Lacosamide alone is unlikely to be a viable therapeutic target for CLN6-Batten disease." (PMID 32269836, 2019). "As such, alteration of CRMP2 activity via (S)-Lacosamide alone is unlikely to be a viable therapeutic target for CLN6-Batten disease, though it may prove to be beneficial when combined with other, synergistic compounds." (PMID 32269836, 2019).
neuronal ceroid lipofuscinosis (15 papers, 2011 to 2025). "CLN6 is an endoplasmic reticulum (ER) membrane protein, and studies have reported that its functional defects lead to neuronal ceroid lipofuscinosis (NCL), with lysosomal dysfunction being a central hallmark of NCL." (PMID 40821828, 2025). "Variant late-infantile neuronal ceroid lipofuscinosis, a fatal lysosomal storage disorder accompanied by regional atrophy and pronounced neuron loss in the brain, is caused by mutations in the CLN6 gene." (PMID 22536393, 2012). "On suspicion of a neurodegenerative disorder in addition to her PWS diagnosis, an urgent trio-WES was performed and detected the homozygous pathogenic variant p.Tyr142fs (NM_017882.3:c.424dup) in the CLN6 gene, consistent with an infantile form of neuronal ceroid lipofuscinosis (OMIM #601708)." (PMID 35886058, 2022). "Mutations in GUSB, CLN6, and PPT1 cause Sly disease, neuronal ceroid lipofuscinosis (CLN6), and neuronal ceroid lipofuscinosis (CLN1), respectively, whereas mutations in GALNS and NAGA cause Morquio A disease and Schindler disease/Kanzaki disease, respectively." (PMID 34867278, 2021). "The most common type was CLN6 (Ceroid lipofuscinosis neuronal) (42%), CLN2 (16%) followed by CLN7 (12%)." (PMID 39281238, 2024). "BMP storage in the brain was described for humans with infantile neuronal-ceroid lipofuscinosis (CLN1 disease) and for mouse models of other types of neuronal-ceroid lipofuscinosis, CLN6 and CLN10 diseases." (PMID 32854299, 2020).
lysosomal storage disorder (5 papers, 2012 to 2024). "A similar phenomenon of slowing autophagy has been observed in the retina of CLN6 mutant mice, which have a lysosomal storage disorder and undergo early retinal degeneration." (PMID 35196199, 2022). "A good example is represented by the patient affected by CLN6, a lysosomal storage disorder in which the clinical presentations can easily mislead to focus on mitochondria, leading to muscle biopsy and RCC assay." (PMID 24215330, 2013).
retinal degeneration (5 papers, 2015 to 2025). Degeneration of the retina. "This study aimed to refine the current description of the CLN6 disease mouse model pathology by determining the age at which retinal layer loss occurs in the Cln6nclf mouse and the precise onset of retinal degeneration." (PMID 40358187, 2025). "We note that disruption of the autophagy-lysosomal pathway followed by abnormal mitochondrial turnover in rod photoreceptors has been suggested to cause early retinal degeneration in mice carrying a mutation in the Cln6 gene (Cln6nclf)." (PMID 33362196, 2020). "Loss of vision due to retinal degeneration is another characteristic symptom of several NCL forms, and has been described in CLN1, CLN2, CLN3, CLN5, CLN6, CLN7 and CLN8 patients." (PMID 25992714, 2015). "This systematic study of the progression of retinal degeneration in distinct sheep models of CLN5 and CLN6 NCL has highlighted the differential vulnerability of retinal cell types in each disease and the time course of degeneration." (PMID 35256654, 2022).
Kufs disease (4 papers, 2020 to 2025). "Now, we know that Kufs disease with progressive myoclonus epilepsy (type A) is associated with mutations in the CLN6 gene, while Kufs disease with dementia and motor disturbances (type B) is linked to mutations in the CTSF gene (also known as CLN13)." (PMID 39925015, 2025). "CLN6 and CLN8 proteins, deficient in CLN6 (also known as Kufs disease) and CLN8 disorders, respectively, form a complex (termed EGRESS: ER-to-Golgi relaying of enzymes of the lysosomal system), which recruits lysosomal enzymes in the ER to facilitate their transfer to Golgi via COPII vesicles." (PMID 33996898, 2021). "The CLN6 gene is also associated with adult‐onset type A Kufs disease." (PMID 32412666, 2020).
CLN6 disease (3 papers, 2014 to 2026). "The implication of apoptosis as a mechanism of neuronal and retinal cell loss in CLN6 disease is confirmed in this mouse model, consistent with observations in the sheep model and in human-CLN6-disease-derived lymphoblasts." (PMID 40358187, 2025). "Given the challenges of in vitro studies in sheep, we further investigated the role of Zip7 in CLN6 disease using mice carrying a natural mutation in Cln6." (PMID 24581221, 2014). "Overall, these findings demonstrate that flupirtine benzyl carbamate diminishes key motor, visual and pathological deficits in CLN6 disease, highlighting its promise as a potential disease-modifying therapy for CLN6 in humans despite sex-specific differences." (PMID 41827875, 2026).
late infantile NCL (3 papers, 2019 to 2025). "CLN6 disease manifests as variant late-infantile NCL (vLINCL) or as an adult variant." (PMID 40358187, 2025). "Biallelic mutations in the CLN7 gene cause the variant late infantile NCL (BD) as do biallelic mutations in CLN5, CLN6 and CLN8 genes." (PMID 41173878, 2025). "Studies have suggested variants of Late-Infantile NCLs (LINCLs) include the major type CLN2 and minor types CLN5, CLN6, CLN7, and CLN8." (PMID 31105743, 2019).
Blindness (2 papers, 2013 to 2025). Blindness is the condition of lacking visual perception defined as a profound reduction in visual perception. "CLN6 loss leads to disease clinically characterized by vision impairment, motor and cognitive dysfunction, and seizures." (PMID 23516525, 2013). "An early manifestation of human CLN6 disease is progressive visual loss, leading to blindness." (PMID 40358187, 2025). "The CLN6 affected sheep appear to be normal for the first few months of life until the most notable disease symptom, blindness, becomes obvious at the age of 10–14 months." (PMID 23516525, 2013).
epilepsy (2 papers, 2021 to 2024). A brain disorder characterized by episodes of abnormally increased neuronal discharge resulting in transient episodes of sensory or motor neurological dysfunction, or psychic dysfunction. "NCL caused by biallelic variants in the CLN6 gene usually presents in early to late childhood to juvenile, between 1.5 and 8 years of age, with slow motor degeneration, ataxia, loss of vision, seizures (epilepsy), and mental disabilities." (PMID 34868216, 2021). "Epilepsy is one of the main symptoms of NCLs caused by CLN6 variants; however, the patients of family 915 did not have epilepsy, and that is in agreement with some other studies." (PMID 34868216, 2021).
Intellectual disability (2 papers, 2019 to 2022). "Including CLN6 in the genetic diagnosis is recommended for individuals presenting with developmental regression, seizures, ataxia, intellectual disability, and ocular symptoms." (PMID 35505348, 2022). "The phenotypic spectrum is highly variable in CLN1 (PPT1) and CLN6 diseases and application of targeted next generation sequencing panels for seizures, intellectual disability or retinopathy, or whole exome sequencing will likely identify more patients with nonclassical NCL phenotypes." (PMID 31741823, 2019).
Kufs disease, Type A (2 papers, 2013 to 2019). "Recent studies have also linked mutations in CLN6 to the adult-onset form of NCL (or Kufs disease, Type A)." (PMID 24223841, 2013).
myoclonic epilepsy (2 papers, 2023 to 2024). A group of epilepsy syndromes in which myoclonic seizures are a prominent feature. "A de novo CLN6 deletion was detected in monozygotic twins who presented with myoclonic epilepsy, making these tests successful in diagnosing some patients." (PMID 39323625, 2024). "Previously, classic CLN3 disease was sometimes loosely considered along with CLN2 and CLN6 to have a progressive myoclonic epilepsy phenotype." (PMID 37039534, 2023).
Brain atrophy (1 paper, 2018). Partial or complete wasting (loss) of brain tissue that was once present. "Overall, ventricular enlargement was more pronounced in CLN5−/− animals than in CLN6−/− animals, which may indicate a differing pattern of brain atrophy in the different types of ovine NCL." (PMID 30136763, 2018).
Cerebellar atrophy (1 paper, 2021). Cerebellar atrophy is defined as a cerebellum with initially normal structures, in a posterior fossa with normal size, which displays enlarged fissures (interfolial spaces) in comparison to the foliae secondary to loss of tissue. "The proband had a homozygous missense CLN6 variant (p.L270P) in exon 7, and he presented with loss of speech, gait abnormality with loss of ambulation, spasticity in the lower limbs, and distal dyskinesia; and brain MRI revealed mild cerebellar atrophy." (PMID 34868216, 2021).
Cerebellar hypoplasia (1 paper, 2023). Cerebellar hypoplasia is a descriptive term implying a cerebellum with a reduced volume, but a normal shape and is stable over time. "Seven probands carry causative variants in well-known genes associated with CA or cerebellar hypoplasia: SETX, CACNA1G, CACNA1A, CLN6, CPLANE1, and TBCD." (PMID 38003592, 2023).
developmental delay (1 paper, 2023). "Specific neurodegenerative diseases, such as GM1-gangliosidosis, caused by GLB1 or ceroid lipofuscinosis caused by CLN6 presented a consistent clinical course of early developmental delay followed by neurologic deterioration, seizures, and generalized spasticity." (PMID 37645600, 2023).
leukoencephalopathies (1 paper, 2018). "Using next-generation sequencing for the genes in a panel for hereditary leukoencephalopathies, we detected a homozygous missense point mutation c.892G > A(p.Glu298Lys) in CLN6, and the variant was interpreted as pathogenic on in silico analysis." (PMID 30285654, 2018).
lung adenocarcinoma (1 paper, 2025). A carcinoma that arises from the lung and is characterized by the presence of malignant glandular epithelial cells. "Our results provide evidence of novel, sensible associations between CLN6 and DHRS1 expression and lung adenocarcinoma survival." (PMID 40685627, 2025). "However, no specific connection between CLN6 and survival of lung adenocarcinoma has been previously found, although a general connection between lysosomal gene expression and survival was established in." (PMID 40685627, 2025).
melanoma (1 paper, 2025). A malignant, usually aggressive tumor composed of atypical, neoplastic melanocytes. "Integrated analysis of survival data from the TCGA database, gene expression profiles, and qRT-PCR validation results indicated that CLN6 may serve as a critical prognosis-related gene in melanoma, warranting further investigation and validation." (PMID 40821828, 2025). "We confirmed the expression patterns of CLN6, GMPR, AP1S2, and ITGA6 in melanoma cells using gene-specific primers by qRT-PCR." (PMID 40821828, 2025).
Parkinson disease (1 paper, 2014). A progressive degenerative disorder of the central nervous system characterized by loss of dopamine producing neurons in the substantia nigra and the presence of Lewy bodies in the substantia nigra and locus coeruleus. "As increased ATP13a2 expression was reported to rescue lysosomal dysfunction in Parkinson’s disease fibroblasts, we hypothesise that upregulation of ATP13a2 in CLN6 affected sheep may similarly compensate to partially improve lysosomal function." (PMID 24581221, 2014).
protein deficiencies (1 paper, 2022). "Recent experimental ocular gene therapies on animal models with soluble lysosomal enzyme deficiencies (CLN1, CLN5, CLN10, and CLN11) and transmembrane protein deficiencies (CLN3 and CLN6) have shown the strong potential of gene therapeutic approaches to effectively treat NCL-related retinopathies." (PMID 35509995, 2022).